AR (androgen receptor)
Diseases named in the same sentence as AR in open-access papers (continued):
Sharing a sentence is not in itself a finding about the gene and the disease.
prostate carcinoma (continued). "In prostate cancer, Dot1l directly methylates androgen receptor to regulate its activity." (PMID 27713173, 2016). "While c-Myc expression is up-regulated rapidly by AR signaling in prostate cancer cells." (PMID 27250340, 2016). "To determine whether KLF4 can regulate AR expression, thereby creating a regulatory loop between AR and KLF4, we analyzed the consequences of modulating KLF4 expression on AR expression in prostate cancer cells." (PMID 27991915, 2016). "Androgen receptor (AR) signaling is crucial during prostate cancer initiation and progression." (PMID 27848972, 2016). "Considering the oncogenic action of miR-21 in BC and the ability of androgens-activated-AR to bind directly to miR-21 promoter increasing its expression in prostate cancer, we evaluated the expression of miR-21 in response to androgen stimulation in BC cells where androgens exert a protective role." (PMID 26862856, 2016). "Therefore, the use of advanced prostate cancer DU145 cell line that lacks functional AR signaling can provide additional avenues for effective management of CRPC." (PMID 27780930, 2016). "The androgen receptor (AR) is the master regulator of prostate cancer cell metabolism." (PMID 27429605, 2016). "Furthermore, androgen receptor (AR) is critical for the development and progression of prostate cancer (PCa) and AR inhibition represents the first-line therapeutic modality for patients with advanced disease." (PMID 27250340, 2016). "In the setting of prostate cancer, AR is a target of CHIP-mediated degradation." (PMID 27007160, 2016). "In addition, the anticancer properties of spices against breast and prostate cancer are related to regulating hormones or hormone receptors, including estrogen receptor and androgen receptor." (PMID 27529277, 2016). "Besides this work and the report focusing on NED in CaP, there are only two other reports on miR-9 in prostate cancer, one being a microarray study and the others focused on the Androgen Receptor (AR)." (PMID 27447934, 2016). "AR has been directly tied to the expression of integrins in prostate cancer." (PMID 27634876, 2016). "The androgen receptor (AR) is required for prostate development and prostate cancer pathogenesis." (PMID 27682980, 2016). "However, little is known about which AR target genes are essential for the proliferation of prostate cancer cells." (PMID 27853318, 2016). "Future ChIP-Seq studies could look into prominent histone modifications accompanying detected response element sites within prostate cancer and facilitate insight how chromatin alteration affects AR gene targeting." (PMID 27623747, 2016). "The oncogenic activity of AR has been intensively studied, mostly in prostate cancer." (PMID 27203692, 2016). "However, there are relatively few studies on AMACR or AR mRNA expression levels in prostate cancer tissue." (PMID 26928323, 2016). "Direct inhibition of the AR has been observed with AT succinate, a more water soluble ester derivative of AT, which has been shown to down-regulate AR protein in androgen-responsive prostate cancer cells." (PMID 26986969, 2016). "We identify a feedback loop between ATP-citrate lyase (ACLY)-dependent fatty acid synthesis, AMPK, and the AR in prostate cancer cells that could contribute to therapeutic resistance by maintaining AR levels." (PMID 27248322, 2016). "In addition, grafts from all patients expressed prostate cancer biomarkers including androgen receptor, PSA, and homeobox protein Nkx3.1." (PMID 27351281, 2016). "Furthermore, the deregulation of AR activity is involved in the initiation of prostate cancer and contributes to castration resistant prostate cancer (CRPC)." (PMID 27835608, 2016). "In prostate cancer cells, OPNc can activate AR signaling and resistance to docetaxel." (PMID 27409830, 2016).
prostate carcinoma (continued). "Importantly, TQ’s down-regulation AR protein expression in human prostate cancer cells is mediated by alterations in cellular oxidative stress that can be abrogated by antioxidants." (PMID 26986969, 2016). "For example, it has been shown that miR-124 could directly target androgen receptor, enhancer of zeste homologue 2, and proto-oncogene tyrosine-protein kinase, which all contribute to prostate cancer progression and treatment resistance." (PMID 27815936, 2016). "Although DDX5 is overexpressed in prostate cancer and functions as a co-activator of the androgen receptor, its functions in hormone-refractory prostate cancer remain unknown." (PMID 27148684, 2016). "c-MET, a close homolog of RON, is suppressed by AR in prostate cancer cell lines." (PMID 26872377, 2016). "Targeting ARD1-mediated AR acetylation may be a potent intervention for AR-dependent prostate cancer therapy." (PMID 27659526, 2016). "Importantly, ASC-J9® also functions through a AR-independent pathway to modulate CCL2 in prostate cancer." (PMID 27564257, 2016). "ACLY expression is elevated in human prostate cancer and correlates with AR expression." (PMID 27248322, 2016). "Notably, in prostate cancer, recurrent rearrangements are frequently observed at androgen-receptor (AR) target genes." (PMID 27552054, 2016). "Regulatory mechanisms of AR and androgen-dependent AR target gene transcription are insufficiently understood and may be critical for prostate cancer initiation, progression and escape from standard therapy." (PMID 27378372, 2016). "AR is the most crucial dysregulated oncogene in prostate cancer." (PMID 26972162, 2016). "Recently, studies demonstrated that some miRNAs might play a role in AR-mediated signals in prostate cancer progression." (PMID 27250340, 2016). "ZEB1 is induced by AR in prostate cancer cells and in triple-negative breast cancer cells." (PMID 26797644, 2016). "Interestingly, ChoK-alpha has also been proposed to act as a chaperone for the androgen receptor, a ligand-inducible transcription factor of the nuclear hormone receptor superfamily, critically involved in prostate cancer progression." (PMID 27532027, 2016). "The vast majority of therapeutic strategies for prostate cancer patients are designed to block AR activity, by either reducing systemic and/or local production of androgens (GnRH agonists, 17α-hydroxylase inhibitors) or by direct competition for the ligand binding pocket of AR (AR antagonists)." (PMID 26918604, 2016). "Finally, we demonstrate that the unrelated MDM2 antagonist Mi-63 also impinges upon AR signalling, supporting the concept of future treatment of prostate cancer with MDM2 antagonists." (PMID 27729622, 2016). "The vast majority of prostate cancer deaths are due to castration-resistant prostate cancer (CRPC) – the lethal form of the disease that has progressed despite therapies that interfere with activation of the androgen receptor (AR)." (PMID 27276681, 2016). "It was previously documented that AR is an inhibitor of prostate cancer metastasis." (PMID 27191265, 2016). "In addition, AR overexpression resulted in a moderate DNAH8 expression increase in multiple prostate cancer cell lines." (PMID 27363033, 2016). "We have shown that prostate cancer (PCa)-associated NANOG is derived primarily from NANOGP8 and is enriched in CD44+ PCa stem/progenitor cells, and inversely correlates with differentiation factors androgen receptor (AR) and prostate-specific antigen (PSA)." (PMID 27867534, 2016). "This pre-clinical study explores co-targeting these pathways in AR-positive prostate cancer models." (PMID 27046225, 2016).
prostate carcinoma (continued). "This puts forth the idea that whereas GR activation has a detrimental effect on AR signaling-deficient prostate cancer, it can also inhibit the progression of prostate cancers from androgen dependence to hormone resistance as long as AR is still functionally active." (PMID 27713909, 2016). "AR regulates the prostate-specific antigen (PSA) expression in prostate cancer cells." (PMID 27399684, 2016). "Given that DANCR promotes the invasion while AR inhibits the invasion of prostate cancer cells, we hypothesized that DANCR may antagonize the effect of androgen-AR on invasion and migration of prostate cancer cells." (PMID 27191265, 2016). "The androgen receptor (AR) is a major drug target in prostate cancer (PCa)." (PMID 26657335, 2016). "Therefore, the resistance mechanisms and molecular pathways involved in changes of AR function as prostate cancer progresses are being increasingly investigated." (PMID 27991915, 2016). "In addition, AR activity contributes to the development, progression, and maintenance of prostate cancer." (PMID 26986969, 2016). "The elevated PHF8 in turn promotes the AR signaling pathway and prostate cancer progression." (PMID 27991916, 2016). "But prostate cancer always escapes from these treatments in support of the hypothesis that a small sub-population of AR− and androgen-independent prostate CSCs is the source of more differentiated AR+ bulk population of prostate cancer cells." (PMID 27378372, 2016). "Therefore, endocrine therapy, mainly through inhibition of AR-signalling activity by antiandrogens (e.g., flutamide, bicalutamide, etc.), has been the mainstay of hormone therapy for prostate cancer over the last few decades." (PMID 28035996, 2016). "The androgen receptor (AR) is the dominant growth factor in prostate cancer (PCa)." (PMID 26572708, 2016). "Therefore, DNAH8 affects both androgen-dependent and -independent prostate cancer cell proliferation, in part by controlling AR activity." (PMID 27363033, 2016). "Our study suggests that the HIFs/PHF8/AR axis is likely a driving force for prostate cancer progression and may also be a target for therapy." (PMID 27991916, 2016). "Prostate cancer growth depend on signaling from the activated androgen receptor (AR)." (PMID 27242530, 2016). "One such combination therapy comprises the AR antagonist bicalutamide and the histone deacetylase (HDAC) inhibitor vorinostat, which act synergistically together to cause death of cell line models of prostate cancer." (PMID 26907477, 2016). "In the course of CRPC development the AR typically switches from being a cell-intrinsic inhibitor of normal prostate epithelial cell proliferation to becoming an oncogene that is critical for prostate cancer cell proliferation." (PMID 27378372, 2016). "AR promoted cell death has been described in several prostate cancer cell lines." (PMID 27203692, 2016). "Therefore, it was proposed that AR can be either tumor suppressor or promoter in prostate cancer, depending on the pathological background." (PMID 27438705, 2016). "Furthermore, qRT-PCR and luciferase analysis also showed that RUNX1 knockdown resulted in the inhibition of androgen-mediated gene and AR transcriptional activity in prostate cancer cells." (PMID 25537508, 2015). "Gene fusions involving the androgen-regulated serine protease TMPRSS2 and ERG, a member of the ETS family of transcription factors, occur in about 50 % of prostate cancers and result in strong AR-driven ERG protein overexpression and massive transcriptional changes." (PMID 26202067, 2015). "Androgen receptor (AR) signaling is essential for the development of prostate cancer." (PMID 25537508, 2015). "In addition to FKBP52, β-catenin, which is a well-documented regulator of AR-mediated transcription, has also emerged as an attractive therapeutic target for prostate cancer treatment." (PMID 26207810, 2015).
prostate carcinoma (continued). "PSMA is a novel and promising target for diagnostics and therapy of metastatic prostate cancer, especially when the androgen receptor is the persistent therapeutic target and pending cross resistances might occur in subsequent androgen-directed therapies." (PMID 26576996, 2015). "In addition to the timing of expression changes in response to androgen stimulation, these data support an AR–ERG–HES1–HES6 transcriptional network in ERG-fusion positive prostate cancer cells." (PMID 25560400, 2015). "PSAP has previously been reported to activate androgen receptor (AR) in prostate cancer cells." (PMID 26341737, 2015). "This transition is typically marked by a gain of function in androgen receptor (AR) signaling, although the transcriptional read-out of such gain may be different from that elicited by AR signaling in hormone-sensitive prostate cancer cells." (PMID 26091350, 2015). "In castration resistant C4-2 prostate cancer cells AR has sustained signaling." (PMID 26154658, 2015). "This has been identified as a potential mechanism that might be crucial in regulating cell growth in the context of malignancy notably in prostate cancer, although the precise mechanisms that underpin ligand-independent AR activation remain unclear." (PMID 25974403, 2015). "This suggests that proliferation may be stimulated by AR independent mechanisms in castration resistant prostate cancer through TMPRSS2-ERG activation." (PMID 25933120, 2015). "In addition, AR-positive, androgen-sensitive VCaP prostate-cancer cells transiently overexpressing OLFM4 displayed reduced expression of SHH and GLI at the mRNA level but not the protein level." (PMID 26581960, 2015). "Elevated expression of AR has been associated with poor survival in prostate cancer and ERα-negative breast cancer patients." (PMID 26397136, 2015). "Hence, it is of great interest to elucidate the regulatory mechanisms involving AR and long noncoding RNAs in prostate cancer." (PMID 26110379, 2015). "This type of cross-talk has been reported to occur with TCDD and estradiol in breast cells and may also play a dominant role in TCDD regulation of AR in prostate cancer." (PMID 26154658, 2015). "AR folding and hormone-dependent activation is dependent upon the dynamic, ordered assembly of heteromeric complexes involving multiple chaperone and cochaperone proteins, many of which are potential therapeutic targets for prostate cancer treatment." (PMID 26207810, 2015). "Interestingly, recent studies have shown that AR signaling regulates prostate cancer growth even under the condition of androgen deprivation in CRPC." (PMID 26506397, 2015). "The crosstalk between AR and Wnt/β-catenin pathways in prostate cancer has been well studied." (PMID 26509262, 2015). "Indeed, significant growth retardation was seen in androgen-sensitive, AR-positive prostate cancer LNCaP cells expressing ELK1-short hairpin RNA (shRNA), compared with control cells, cultured in the presence of androgen." (PMID 26342199, 2015). "AR is known to promote cell proliferation in prostate cancer in androgen dependent manner." (PMID 25781993, 2015). "Studies have shown that a novel constitutively active AR splice variant lacking most of the LBD domain mediates prostate cancer anti-androgen therapy resistance." (PMID 26622945, 2015). "Finally, phosphorylation of androgen receptor by CDK5 plays a role in driving prostate cancer growth." (PMID 26509276, 2015). "Similar to what we have observed at p63 binding sites, well-positioned nucleosomes near TF binding sites have been reported at the Pu.1 sites in macrophages and the androgen receptor sites in prostate cancer cells, although the basis for this positioning is unclear." (PMID 26683334, 2015). "CDK5 also showed to promote prostate cancer cell growth through androgen receptor." (PMID 26205145, 2015). "It was previously reported that NLK could interact with the wild-type AR in prostate cancer cell lines." (PMID 26308581, 2015).
prostate carcinoma (continued). "Furthermore, a decrease in LMTK2 protein expression, as proposed in prostate cancer, not only results in an increase in androgen mediated AR activity but also increases the androgen-independent activity of AR." (PMID 26008968, 2015). "Therapies with AR antagonists such as bicalutamide (Casodex) and androgen withdrawal initially regress tumors but development of various compensatory mechanisms including AR bypass signaling leading to tumor growth, and eventually develop more aggressive castration resistant prostate cancer (CRPC)." (PMID 25971429, 2015). "In males, the AR has been shown to play a key role in prostate cancer genesis and progression." (PMID 26347776, 2015). "KDM3A also regulates androgen receptor (AR) activity in prostate cancer cell lines." (PMID 25488809, 2015). "Its inhibition attenuates the viability of prostate cancer cells and decreases the transactivation activity of AR, which indicates that PRNCR1 could be involved in prostate carcinogenesis through an AR-mediated pathway." (PMID 26110379, 2015). "Targeting AR with celastrol for prostate cancer treatment has been shown by several groups." (PMID 26473737, 2015). "While investigating MB protein expression in prostate cancer, a significant positive correlation to androgen-receptor (AR) staining was observed and the analysis of publicly available transcriptome data suggested a dihydrotestosterone (DHT)-mediated suppression of the MB gene." (PMID 26559958, 2015). "Both in vivo and in vitro experiments suggest that TCDD, acting as an endocrine disruptor, may affect androgen receptor function and contribute to the development of prostate cancer." (PMID 26154658, 2015). "Androgen receptor (AR) signaling in stromal cells is important in prostate cancer, yet the mechanisms underpinning stromal AR contribution to disease development and progression remain unclear." (PMID 25965833, 2015). "Recently, studies reported that AR may function as both suppressor and proliferator to suppress or promote prostate cancer metastasis." (PMID 26491675, 2015). "Finally, KDM4B, which itself is regulated by androgens, can stimulate AR-mediated transcription not only via demethylation activity but also via modulation of ubiquitination in prostate cancer cells." (PMID 26397136, 2015). "An effective prostate cancer treatment is chemical castration using luteinizing hormone-releasing hormone analogues to ablate testicular androgens or use of antiandrogens (e.g., flutamide), which block androgen signaling at the level of the AR." (PMID 26347776, 2015). "Suppression of GRβ by siRNA inhibited growth of AR positive prostate cancer cells." (PMID 26347776, 2015). "We thus reasoned that the CXCL11/CXCR7 axis may also engage the AR signaling pathway in human prostate-cancer cells." (PMID 25884570, 2015). "Elevated blood cholesterol levels may enhance the androgen receptor pathway via intratumoral de novo androgen synthesis in the prostate, contributing to prostate cancer progression." (PMID 25924234, 2015). "In this study, we demonstrated not only a significant inhibition of growth of prostate cancer cells by curcumin, but more importantly, a synergistic effect observed in combination of curcumin with bicalutamide, an androgen receptor antagonist, in androgen-independent prostate cancer cells." (PMID 25971429, 2015). "This Registered Report describes the proposed replication plan of key experiments from “The Androgen Receptor Induces a Distinct Transcriptional Program in Castration-Resistant Prostate Cancer in Man” by Sharma and colleagues (2013), published in Cancer Cell in 2013." (PMID 26401447, 2015). "Furthermore, since the AR program regulates the transcriptional programs of DNA repair genes in prostate cancer cells, AR axis inhibition has the potentially undesirable side-effect of promoting genomic instability." (PMID 25896606, 2015).